CCNB1 (cyclin B1)
Diseases named in the same sentence as CCNB1 in open-access papers (continued):
Sharing a sentence is not in itself a finding about the gene and the disease.
melanoma (42 papers, 2008 to 2026). A malignant, usually aggressive tumor composed of atypical, neoplastic melanocytes. "In vivo, pharmacological inhibition of the CCNB1/Cyclin-dependent kinase 1 (CDK1) complex with RO-3306 significantly suppressed melanoma growth by enhancing NK cell infiltration and IFN-γ production." (PMID 40430484, 2025). "We confirmed that CCNB1 knockdown reduced PD-L1 at both transcriptional and protein levels in melanoma cells." (PMID 40430484, 2025). "Specifically, TGF-β emerged as the dominant signaling pathway in CCNB1-high melanoma, with network analysis revealing that these cells received stronger TGF-β signals from various sources, including NK cells." (PMID 40430484, 2025). "This study highlights the critical role of CCNB1/CDK1 in melanoma resistance to NK cell-mediated cytotoxicity and tumor invasiveness." (PMID 40430484, 2025). "Western blot analysis revealed increased TGF-β1 levels and activation of the SMAD2/3 pathway in CCNB1-overexpressing melanoma cells, whereas CCNB1 knockdown led to reduced TGF-β1 expression and inhibition of SMAD2/3 signaling." (PMID 40430484, 2025). "In this study, we constructed a risk model based on NK cell activation-related genes and identified CCNB1 as a druggable target driving melanoma resistance to NK cell-mediated cytotoxicity." (PMID 40430484, 2025). "According to the RT-PCR results, CCNA2 and CCNB1 expression levels decreased across all canine melanoma cell lines, whereas CCND1 expression was notably increased." (PMID 40642276, 2025). "In this study, we provide the first direct evidence that CCNB1 enhances melanoma cell resistance to NK cell-mediated cytotoxicity (summary diagram)." (PMID 40430484, 2025). "These dual effects suggest that CCNB1/CDK1 is a promising therapeutic target in melanoma and warrants further investigation." (PMID 40430484, 2025). "In vitro, CCNB1 knockdown in melanoma cells augmented NK-92MI activation, as evidenced by increased expression of CD69, CD107a, IFN-γ, and NKG2D, thereby improving NK cell-mediated cytotoxicity." (PMID 40430484, 2025). "Our results showed that CCNB1 knockdown led to an upregulation of MICA/MICB expression in melanoma cells, and a corresponding increase in NKG2D expression in NK-92MI cells." (PMID 40430484, 2025). "In the GSE115978 dataset, melanoma cells with high CCNB1 expression exhibited enhanced cell–cell communication, particularly stronger interactions with NK cells, T cells, macrophages, and CAFs (left)." (PMID 40430484, 2025). "Beyond its role in immune evasion, CCNB1 also promoted melanoma invasiveness by inducing epithelial–mesenchymal transition (EMT) through the TGF-β-SMAD2/3 signaling." (PMID 40430484, 2025). "Together, these results demonstrated that CCNB1 knockdown enhances NK cell activation and cytotoxicity, promoting melanoma cell apoptosis in vitro." (PMID 40430484, 2025). "In the GSE189889 dataset, we observed that CCNB1 expression levels correlated with melanoma–NK cell interactions." (PMID 40430484, 2025). "Our results demonstrated that CCNB1-high melanoma cells secrete elevated IL-6, a known activator of STAT3 signaling in NK cells." (PMID 40430484, 2025). "In vitro, we confirmed that the CCNB1/CDK1 inhibitor RO-3306 suppresses melanoma growth while boosting NK cell infiltration and activation." (PMID 40430484, 2025). "To better understand the role of CCNB1-high melanoma cells in the tumor microenvironment (TME), we applied CellChat, a machine-learning-based method, to analyze single-cell RNA-seq datasets (GSE115978 and GSE189889)." (PMID 40430484, 2025). "In contrast, our study developed a gene-based prognostic model to predict NK cell activation and melanoma prognosis, identifying CCNB1, PRKACB, FCGR2C, and CCL8 as key prognostic genes." (PMID 40430484, 2025).
melanoma (continued). "Mechanistically, in melanoma cells, the CCNB1/CDK1 complex phosphorylates STAT3, activating the IL-6/STAT3 positive feedback loop, which upregulates PD-L1 and enables resistance to NK cell-mediated cytotoxicity." (PMID 40430484, 2025). "Overall, the interaction between CCNB1-high melanoma cells and NK cells in the tumor microenvironment is complex, requiring further studies to validate key mechanisms." (PMID 40430484, 2025). "To further validate the specific role of CCNB1 in driving NK cell dysfunction in melanoma, we used NK-92MI cells, an IL-2-independent NK cell line widely used in studies on NK cell therapy and immune tolerance." (PMID 40430484, 2025). "More directly, the release of IFN-γ from NK-92MI was significantly upregulated in the co-culture with CCNB1 knockdown melanoma cells." (PMID 40430484, 2025). "Our findings highlighted that CCNB1 enables melanoma cells to evade NK cell-mediated immunity by activating the CDK1-STAT3 signaling axis, leading to increased IL-6 and PD-L1 expression." (PMID 40430484, 2025). "Based on CCNB1 expression levels, melanoma cells were classified into high and low CCNB1 groups to explore interaction patterns with immune and stromal cells." (PMID 40430484, 2025). "Given the dual oncogenic role of CCNB1 in resisting NK cell-mediated killing and enhancing melanoma invasiveness, we propose that CCNB1/CDK1 inhibitors represent a promising strategy to enhance NK cell-based immunotherapy for melanoma." (PMID 40430484, 2025). "Lower levels of Cyclin B1 were observed in parental cells compared with BRAFi resistant melanoma cells after treatment with AURK inhibitor." (PMID 35444937, 2022). "Conversely, Cyclin B1 expression remained constant in all the analyzed melanoma cell lines except at 8 μM dose, where it suddenly increased." (PMID 35371312, 2022). "The result was consistent with the Western blot analysis of CCNB1 (one of representative cell cycle regulators), and with the melanoma cell cycle arrest after mitochondrial administration by using flow cytometry." (PMID 34131403, 2021). "Taken together, DET and DETD-35 induced G2/M phase arrest in A375LM5IF4g/Luc melanoma lung-seeking cells by affecting the cdk1/cyclin B1 complex regulation and G2 to M transition." (PMID 33810045, 2021). "By using the same paraffin sections for the expression of ERs, we detected strong CCNB1 expression in malignant melanoma tissues in 10/20 patients (50%), moderate expression in 5/20 patients (25%), and mild expression in 5/20 patients (25%)." (PMID 31696058, 2019). "For evidence linking ERβ and CCNB1 expression to the progression of melanoma, immunohistochemical analyses were performed from the paraffin sectioned in human melanomas samples." (PMID 31696058, 2019). "Our data reveal that C3G promoted melanoma cell apoptosis both in vitro and in vivo by binding to the ERβ, which, in turn, inhibited the expression of CCNB1 and triggered the apoptosis pathway." (PMID 31696058, 2019). "The dysregulated expression of CCNB1 is observed in many different cancers, including melanoma and esophageal squamous cell carcinoma." (PMID 31007608, 2019). "Data showed enrichment of both binding sites within the CCNB1 promoter region, indicating that the increases of mRNA and subsequent protein levels of CCNB1 in melanoma cell lines are likely due to a direct interaction of ERβ with the CCNB1 gene promoter." (PMID 31696058, 2019). "By using the ChIP assay with the ERβ antibody in melanoma cell, we also demonstrated that CCNB1 is a direct target of ERβ." (PMID 31696058, 2019). "We further demonstrated that Pearson's correlation coefficient between ERβ and CCNB1 was −0.577 (P = 0.008) from 20 paraffinized melanoma samples." (PMID 31696058, 2019). "By mining the data from the Human Protein Atlas, we found an inverse correlation between survival rate and CCNB1 levels in melanoma patients." (PMID 31696058, 2019).
melanoma (continued). "Compared with neonatal human epidermal melanocytes, BRAFV600E-mutated Colo829 human melanoma cells showed enhanced expression of Pin1, FOXM1, CENPF and Cyclin B1 both at the mRNA and protein levels." (PMID 26279295, 2016). "Most importantly, PEI-mediated systemic delivery of sticky siRNAs against survivin and cyclin B1 efficiently blocks growth of established subcutaneaous B16-F10 tumors as well as formation and dissemination of melanoma lung metastases." (PMID 23835136, 2013). "Our results show that ssiRNAs are efficient to inhibit survivin and cyclin B1 expression in vitro and that a systemic treatment with ssiRNAs targeting these two genes is able to reduce both subcutaneous melanoma tumors and their lung metastases." (PMID 23835136, 2013). "PEI-mediated delivery of sticky siRNAs targeting genes involved in tumor progression such as survivin and cyclin B1, either alone or in combination with chemotherapeutic drugs, represents a promising strategy for melanoma treatment." (PMID 23835136, 2013). "We used this new technology to specifically target survivin and cyclin B1 in B16-F10 murine melanoma cells." (PMID 23835136, 2013). "Altogether, our data are promising towards development of ssiRNAs against survivin and cyclin B1 as a new therapeutic strategy for melanoma treatment." (PMID 23835136, 2013). "Studies in different human tumors and cell lines including breast, lung, colorectal, lymphoma, leukemia, and melanoma have detected increased levels of cyclin B1 at both protein and mRNA." (PMID 19036130, 2008). "Additionally, we demonstrated that CCNB1 promotes melanoma EMT and invasiveness through the TGF-β-SMAD2/3 signaling." (PMID 40430484, 2025). "Our findings suggest that CCNB1 expression in melanoma cells may impair NK cell cytotoxicity by modulating both intrinsic tumor properties and NK cell activation status." (PMID 40430484, 2025). "Conversely, in CCNB1-low melanoma, melanoma cells exhibited enhanced intrinsic CDH signaling." (PMID 40430484, 2025). "Additionally, we examined the MICA/MICB-NKG2D axis, a crucial mechanism for NK cell-mediated tumor recognition and killing, and found that CCNB1-high melanoma cells suppress its activation." (PMID 40430484, 2025). "In co-culture with two melanoma cell lines, ME4405 and SK-MEL-28 (which harbor BRAF and NRAS mutations, respectively), we observed that knockdown of CCNB1 in melanoma cells increased the proportion of NK-92MI expressing CD69 and CD107a, which are key markers of NK cell activation." (PMID 40430484, 2025). "Indeed, treating NK-92MI cells with supernatant from CCNB1-overexpressing melanoma cells activated STAT3 signaling." (PMID 40430484, 2025). "Finally, Transwell invasion assays demonstrated that silencing CCNB1 significantly reduced melanoma cell invasiveness." (PMID 40430484, 2025). "Our cell–cell communication analysis revealed that CCNB1-high melanoma cells may significantly impact interactions with the tumor microenvironment, particularly with NK cells, which can transmit TGF-β signals to melanoma cells and influence EMT." (PMID 40430484, 2025). "Notably, IL-6 secreted by CCNB1-high melanoma cells not only maintains STAT3 activation within tumor cells but also enhances STAT3 signaling in NK-92MI cells, potentially exacerbating NK cell dysfunction." (PMID 40430484, 2025). "In addition, we demonstrated that MTAP-ANRIL enhanced melanoma cell proliferation by upregulating the expression of the cell cycle regulators, cyclin B1 and cyclin D1." (PMID 37277447, 2023).
melanoma (continued). "Taken together, these data suggest that differential regulation of Cyclin B1 degradation dictates whether MLN8237-treated melanoma cells undergo mitotic slippage or prolonged cell cycle arrest and subsequent loss of viability." (PMID 35444937, 2022). "Compared to normal melanocytes, iASPP, MDM2 and cyclin B1 are often overexpressed in melanoma." (PMID 34911439, 2021). "Moreover, 2-ME treatment decreases pRb and cyclin B1 expression, increases p21/Cip1 expression, and induces G2/M cell cycle arrest in both 2D and 3D melanoma cellular models." (PMID 32082378, 2019). "Furthermore, an inverse correlation was confirmed between expression levels of ERβ and CCNB1 in melanoma by mining data from the TCGA." (PMID 31696058, 2019). "Moreover, they reported that ERβ agonists exert antiproliferative activities in BLM melanoma cells by modulating cell cycle progressing factors (CCNB1, CCND3, and p27) and by blocking the G1-S transition phase without triggering the apoptosis pathway." (PMID 31696058, 2019). "Specifically, we observed significantly reduced CCNB1 expression at the transcriptional level in response to C3G, and that ERβ may be a favorable prognostic factor for melanoma." (PMID 31696058, 2019). "We used our newly developed sticky siRNA-based technology delivered with linear polyethyleneimine (PEI) to inhibit the expression of survivin and cyclin B1 both in vitro and in vivo, and addressed the effect of this inhibition on B16-F10 murine melanoma tumor development." (PMID 23835136, 2013). "Furthermore, several studies have demonstrated its clinical significance as a poor prognosis factor for several cancer types, including melanoma, and cyclin B1 overexpression is responsible for radiotherapy resistance in different tumors." (PMID 23835136, 2013). "Additionally, EMT-related signaling pathways, including CDH, CDH1, WNT, Laminin, Collagen, and Tenascin, were more active in CCNB1-high melanoma, with both incoming and outgoing signaling interactions strengthened, whereas these signals weakened in CCNB1-low melanoma." (PMID 40430484, 2025). "Meanwhile, CCNB1 upregulates TGF-β expression and secretion, inducing EMT and enhancing melanoma invasiveness." (PMID 40430484, 2025). "The Q1 cohort demonstrated significantly elevated expression of CCNA2, CCNB1, CCND1, and CDH2, indicating CDC25A’s potential regulatory role in coordinating melanoma cell cycle progression with EMT dynamics." (PMID 40216745, 2025). "Inhibition of the JNK and p38 pathways in MTAP-ANRIL melanoma cells increased the expression level of E-cadherin but decreased the expression levels of SNAIL1, N-cadherin, cyclin B1 and cyclin D1 that were increased by MTAP-ANRIL." (PMID 37277447, 2023). "The analysis showed significant downregulation of phosphorylated cyclin B1 in A2058 and BLM melanoma cells after treatment with chalcone 1C with maximum after 72 h in both cell lines." (PMID 36293123, 2022). "To examine the function of p75NTR‐FL/CTF in melanoma, we quantified the mRNA levels of cell‐cycle effectors, including cyclin‐dependent kinase 2 (CDK2), CDK4, cyclin D1, cyclin B1 and cyclin‐dependent kinase 1 (cdc2), by quantitative RT‐PCR (qRT‐PCR)." (PMID 33247998, 2021). "For example, the expression levels of cyclin B1, the regulatory unit of CDK1/cyclin B1 complex important for the transition of G2/M is known to be higher in late stage melanomas compared to benign nevi." (PMID 30745871, 2019).
melanoma (continued). "We therefore validated that the gene expression of AURKA, CCNB1 and CDKN3 was upregulated upon UV-irradiation of Group 3 FM SF cultures and compared the expression of these genes in normal skin and melanoma tissue." (PMID 23371019, 2013). "Our analyses pointed out a down modulation of cell cycle regulators cyclin B1, cdc25B, and CDK4, which certainly contributes to the inhibition of cell proliferation exerted by D6 on melanoma cells." (PMID 23642048, 2013). "HEI10 was also found to be overexpressed in melanoma, and heterologous expression led to a model in which HEI10 regulates G2/M transition in mammals by controlling Cyclin B1 levels." (PMID 22844245, 2012). "This suggests that CCNB1-driven IL-6 secretion may stimulate NK cells to release pro-invasive signals such as TGF-β, which in turn promotes melanoma invasiveness." (PMID 40430484, 2025). "First, we primarily focused on how CCNB1 mediates immune tolerance in melanoma cells but did not investigate how the upregulated TGF-β affect NK cells and other immune cells in the tumor microenvironment." (PMID 40430484, 2025). "Additionally, we found that CCNB1 directly enhances TGF-β production and secretion in melanoma cells, activating the SMAD2/3 pathway to drive EMT and tumor invasion." (PMID 40430484, 2025). "RO-3306, a CCNB1/CDK1 inhibitor, can simultaneously inhibit the activity of both CCNB1 and CDK1, and has previously been shown to suppress tumor-initiating capacity in melanoma by disrupting CDK1-Sox2 signaling." (PMID 40430484, 2025). "Additionally, CCNB1 activates the TGF-β-SMAD2/3 pathway, driving EMT and enhancing melanoma invasiveness." (PMID 40430484, 2025). "Furthermore, we demonstrated that C3G treatment arrested the cell cycle at the G2/M phase by targeting cyclin B1 (CCNB1) and promoted apoptosis via ERβ in both mouse and human melanoma cell lines, and inhibited melanoma cell growth in vivo." (PMID 31696058, 2019). "Furthermore, the expression levels of CCNA2, CCNB1, CDK1, and CDK4 decreased in melanoma cells treated with metformin, whereas the levels of p21 and CCND1 increased." (PMID 30754729, 2019). "Thus, one important regulator of CDK1/cyclin B1 complex, CDC25C, is suggested to be a potential oncotarget for melanoma." (PMID 30745871, 2019). "Individual melanomas from independent data sets showed that FOXM1, CENPF and Cyclin B1, but not actin (control), significantly correlated with Pin1 expression." (PMID 26279295, 2016).